FKBP7 (FKBP prolyl isomerase 7)
Description:
PPIases accelerate the folding of proteins during protein synthesis.
Synonyms: FKBP23; PPIase
Tractability: Small molecule: it belongs to a druggable protein family. Antibody: UniProt predicts a signal peptide or a membrane-spanning region.
Gene: Protein-coding gene on chromosome 2 (178,463,664 to 178,478,600, reverse strand). Ensembl gene ENSG00000079150.
Subcellular location: Endoplasmic reticulum lumen
Subcellular location (Human Protein Atlas): Endoplasmic reticulum
Gene Ontology:
Molecular function: protein binding; FK506 binding; peptidyl-prolyl cis-trans isomerase activity; calcium ion binding
Cellular component: endoplasmic reticulum; endoplasmic reticulum lumen
Genetic constraint (gnomAD): Loss-of-function variants: 21 observed, 22.58 expected, observed/expected ratio (o/e) 0.93, 90% interval 0.66 to 1.34. The upper end of that interval is the gene's LOEUF score, 1.34, which puts it in group 5 of 6, group 1 being the genes least tolerant of losing a copy. Missense variants: 251 observed, 273.49 expected, observed/expected ratio (o/e) 0.92, 90% interval 0.83 to 1.02. Synonymous variants: 95 observed, 94.37 expected, observed/expected ratio (o/e) 1.01, 90% interval 0.85 to 1.19.
Homologues: Orthologues: chimpanzee FKBP7 (99% identical), macaque FKBP7 (98% identical), pig FKBP7 (90% identical), rabbit FKBP7 (88% identical), dog FKBP7 (88% identical), guinea pig FKBP7 (86% identical), mouse Fkbp7 (86% identical), rat Fkbp7 (69% identical), tropical clawed frog fkbp7 (63% identical), zebrafish fkbp7 (56% identical), Caenorhabditis elegans fkb-5 (23% identical), Caenorhabditis elegans fkb-4 (21% identical), and 1 more. Paralogues in human: FKBP14 (45% identical), FKBP9 (29% identical), FKBP10 (28% identical), FKBP5 (28% identical), FKBP4 (24% identical), FKBP15 (23% identical), FKBP3 (21% identical), FKBP11 (20% identical), FKBP2 (20% identical), FKBP8 (17% identical), FKBP6 (16% identical), FKBP1A (15% identical), and 6 more.
Diseases named in the same sentence as FKBP7 in open-access papers:
FKBP7 is named in the same sentence as 9 diseases in open-access papers, as found by Europe PMC text mining. Sharing a sentence is not in itself a finding about the gene and the disease. The quoted sentences say what the papers report.
atrial fibrillation (3 papers, 2022 to 2026). A disorder characterized by an electrocardiographic finding of a supraventricular arrhythmia characterized by the replacement of consistent P waves by rapid oscillations or fibrillatory waves that vary in size, shape and timing and are accompanied by an irregular ventricular response. "GWAS data have shown that FKBP7 is a marker of increased risk and a therapeutic target of atrial fibrillation (AF)." (PMID 41541644, 2026). "PRKRA has been implicated in studies impacting heart structure, and while FKBP7 has been less discussed, was linked to atrial fibrillation in one study." (PMID 39670392, 2025).
dilated cardiomyopathy (1 paper, 2025). Cardiomyopathy which is characterized by dilation and contractile dysfunction of the left and right ventricles. "It is worth noting that FKBP7, PRKRA, and third gene (PLEKHA3, significant with LVM, LVEDV, and LVESV), all lie within a region of chromosome 2 that also includes the gene TTN, which is well established heritable cause of dilated cardiomyopathy, a leading cause of heart failure." (PMID 39670392, 2025).
melanoma (1 paper, 2016). A malignant, usually aggressive tumor composed of atypical, neoplastic melanocytes. "FK506 family member FKBP51 promotes melanoma metastasis in vivo but nothing is known about the role of FKBP7, 10 and 11 in melanoma growth." (PMID 27689402, 2016). "Whereas the role of TNC (tenascin C) and FN1 (fibronectin 1) in melanoma development is well documented, implication of MARCKS, RCN3, BAMBI, PEA3/ETV4 and the FK506 family members FKBP7, FKBP10 and FKBP11 in melanoma progression is unclear." (PMID 27689402, 2016).
skin cancer (1 paper, 2016). "FKBP7, FKBP11 and FKBP10, upregulated 3.21, 2.42 and 15.18-fold, respectively, have not yet been described in skin cancer." (PMID 27689402, 2016).
infection (1 paper, 2024). The state of being infected such as from the introduction of a foreign agent such as serum, vaccine, antigenic substance or organism. "Proteins associated with any persistent symptom attributed to long COVID at ten months post-infection included FKBP7, which accelerates the folding of proteins during protein synthesis, and COMMD7, which associates with the NF-kappa-B complex and suppresses its transcriptional activity." (PMID 39324144, 2024).
FKBP7 also shares sentences with these, for which no sentence is quoted: cancer (2 papers); COVID-19 (1); lung carcinoma (1); ovarian carcinoma (1).